MYD88 (MYD88 innate immune signal transduction adaptor)
Diseases named in the same sentence as MYD88 in open-access papers (continued):
Sharing a sentence is not in itself a finding about the gene and the disease.
acute lung injury (7 papers, 2020 to 2025). A condition of lung damage that is characterized by bilateral pulmonary infiltrates (pulmonary edema) rich in neutrophils, and in the absence of clinical heart failure. "MicroRNA-7704 (miR-7704) has been identified as a potential therapeutic target for acute lung injury (ALI) by promoting M2 macrophage polarization through inhibition of the MyD88/STAT1 signaling pathway." (PMID 41296398, 2025). "Similar to our findings, a study focused on the effect of paeonol on acute lung injury (ALI) has demonstrated that paeonol ameliorates LPS-induced ALI via inhibition of the TLR4/MyD88/NF-κB signalling pathway." (PMID 35303801, 2022). "Myeloid differentiation factor 88 (MyD88) is a hub protein in the Toll-like receptor signaling pathway, which acts as a master switch for numerous inflammatory diseases, including acute lung injury (ALI)." (PMID 34912226, 2021). "Our results are in agreement with other reports that baicalin, a bioactive component of QHSG, inhibits the secretion of inflammatory factors in LPS-induced acute lung injury in rats by suppressing the TLR4/myeloid differentiation factor 88 (MyD88)/NF-κB signaling pathway." (PMID 37954597, 2023).
allergic asthma (7 papers, 2010 to 2026). A asthma with a basis in a pathological type I hypersensitivity reaction. "We have previously demonstrated that CpG has a prophylactic effect in allergic asthma that is dependent of MyD88 signaling." (PMID 32391011, 2020). "MyD88 signaling is essential for CP infection induced antigen sensitization in this allergic asthma model." (PMID 21695198, 2011). "Furthermore, the intranasal administration of PN has been shown to activate the MAPKs pathway and induce the production of TSLP and IL-25 independently of the IL-1R1/MyD88 signaling in a mouse model of allergic asthma." (PMID 39199175, 2024). "Study in allergic asthma mice and MHS alveolar macrophages further demonstrate that the damage-associated molecular pattern S100A8/A9 enhances glycolysis and lactate production via TLR4/MyD88/NF-κB signaling, concomitant with increased ACLY phosphorylation and upregulation of M1 signature factors." (PMID 41602451, 2026). "In an allergic asthma model, calprotectin S100A8/A9 drives M1 polarization via the TLR4/MyD88/NF κB axis and markedly augments glycolysis, as indicated by raised lactate and glycolytic enzymes." (PMID 41602451, 2026). "S100A8 and S100A9 play critical roles in allergic asthma pathogenesis by promoting macrophage perturbation and glycolysis through the TLR4/MyD88/NF-κB signaling pathway." (PMID 38646478, 2024). "Our study highlights that S100A8 and S100A9 play critical roles in the pathogenesis of allergic asthma by promoting macrophage perturbation and glycolysis through the TLR4/MyD88/NF-κB signaling pathway." (PMID 38646478, 2024). "The TLR4/MyD88/TRIF/NF-κB signaling pathway and ACLY activity were inhibited in OVA-induced MH-S cells with knockdown of S100A8 or S100A9 and allergic asthma mice, suggesting that knockdown of S100A8 or S100A9 inhibits glycolysis by suppressing the TLR4/MyD88/TRIF/NF-κB signaling pathway." (PMID 38646478, 2024).
Cirrhosis (7 papers, 2017 to 2026). A chronic disorder of the liver in which liver tissue becomes scarred and is partially replaced by regenerative nodules and fibrotic tissue resulting in loss of liver function. "In parallel, genes activated by LPS including myeloid differentiation factor 88 (Myd88) and interferon regulatory factor 3 (Irf3) were upregulated in inflammation and cirrhosis compared to advanced cirrhosis and HCC (all P < 0.001)." (PMID 33858327, 2021). "CXCR3 knockdown suppresses TLR4/MyD88, BIRC, and COL1A1 expression, inhibits proliferation and migration, and promotes apoptosis, thereby attenuating cirrhosis-to-carcinoma transition." (PMID 41258710, 2026). "Based on in vitro experiments, IGF-1 might serve as a potential therapeutic target for cirrhosis and intestinal barrier dysfunction via its inactivation of the TLR4/MyD88/NF-κB pathway." (PMID 36330225, 2022).
cryptococcosis (7 papers, 2007 to 2024). An acute or chronic, localized or disseminated infection by Cryptococcus neoformans. "The adapter protein associated with TLR, the MyD88 molecule, is known to play an important role in the immune response, since animals who are deficient in MyD88 showed an increased susceptibility to cryptococcosis." (PMID 38786693, 2024). "The TLR-associated adapter protein, MyD88, is known to play an important role in immune response to C. neoformans, as mice deficient in MyD88 have increased susceptibility to Cryptococcosis." (PMID 31275938, 2019). "The importance of MyD88 in host defense in cryptococcal infection was demonstrated when MyD88-deficient mice exhibited decreased survival and increased fungal burden in the lungs following fungal challenge." (PMID 22039448, 2011). "Signaling via the adapter protein, MyD88, is important in the host defense against Cryptococcus neoformans infection." (PMID 22039448, 2011). "Previous studies have shown that MyD88 and certain TLRs contribute to host protective responses in cryptococcal infection." (PMID 22039448, 2011). "In summary, we found that multiple signaling components can contribute the MyD88-dependent host responses to cryptococcal infection in vivo and each drives distinct pulmonary responses." (PMID 22039448, 2011). "Our experimental findings suggest that IL-18R and TLR9 significantly contribute to MyD88-dependent host defense in cryptococcal infection." (PMID 22039448, 2011). "Since the increased susceptibility of TLR2−/− mice to cryptococcosis is not as pronounced as that of MyD88−/− mice, MyD88 may mediate non-TLR signaling in response to C. neoformans as well." (PMID 28936464, 2017). "Whether TLR signaling is relevant to human disease is unclear, as people with Mendelian defects in MyD88 do not have increased susceptibility to cryptococcosis." (PMID 28936464, 2017). "More recently MyD88 and TLR2 but not TLR4 were shown to be required for host defense against Cryptococcus neoformans infection." (PMID 17982419, 2007).
E. coli infection (7 papers, 2018 to 2025). "Since Myd88 serves as an adapter for other TLRs, these data suggest that other pattern recognition receptors are engaged during E. coli infection and are critical for control of infection beyond liver abscess formation." (PMID 38096412, 2023). "Pretreatment with three different doses of L. plantarum 17–5 significantly reduced the expression of TLR2, TLR4 and MyD88 mRNA after E. coli infection (P < 0.05)." (PMID 35764986, 2022). "Different from E. coli infection, S. aureus infection induced IRF7 and phosphorylation of IRF7 through activating TRAF3‐IKKε/TBK1 axis, bypassing MyD88." (PMID 39166412, 2024). "The results showed that E. coli infection in mice activated the TLR4/MyD88/NF-κB signaling pathway, but mice pretreated with 4-PBA did not obviously activate the TLR4/MyD88/NF-κB signaling pathway." (PMID 40076603, 2025).
experimental autoimmune encephalomyelitis (7 papers, 2014 to 2022). An autoimmune demyelinating disease of the central nervous system that is produced experimentally in animals by the injection of homogenized brain or spinal cord in Freund's adjuvant. "However, in a spontaneous mouse model of experimental autoimmune encephalomyelitis, development of disease was not prevented by loss of the MyD88 gene." (PMID 25229618, 2014). "Immunosuppressive properties of B cells, especially the production of IL-10 in experimental autoimmune encephalomyelitis (EAE) mice model is dependent on toll-like receptor-2 (TLR-2), toll-like receptor-4 (TLR-4)and myeloid differentiation primary response 88 (MyD88) signaling." (PMID 34867973, 2021).
glomerulonephritis (7 papers, 2014 to 2024). A renal disorder characterized by damage in the glomeruli. "It was suggested that canonical toll-like receptor signaling, mediated by the adaptor protein MYD88, plays a crucial role in initiating inflammatory responses in glomerulonephritis (GN)." (PMID 38280906, 2024). "It has been reported that autoantibody production and urine protein due to glomerulonephritis in MRL/lpr mice depend on B cell-intrinsic MyD88 signal." (PMID 32117252, 2020).
MALT lymphoma (7 papers, 2013 to 2025). An indolent, extranodal type of non-Hodgkin lymphoma composed of small B-lymphocytes (centrocyte-like cells). "MYD88 mutation is infrequent in MALT lymphomas altogether, which is in contrast to primary ocular adnexa MALT lymphoma (OAMZL) where MYD88 mutation, mainly L265P, occurs at frequencies about 6–7%." (PMID 35008340, 2021). "MYD88 L265P mutations may occur in a minority of cases of MALT lymphoma (6–9%) at different sites, including lung." (PMID 33499258, 2021). "MYD88 is also affected by somatic mutations in 10% of NMZL and MALT lymphomas." (PMID 34590593, 2021). "Beyond TNFAIP3 and MYD88 mutations, MALT lymphoma shows rare or no mutations in other members of NF-kB pathway such as CD79A, CD79B, CARD11, BIRC3, and TNFRSF11A, which are frequently seen in other B-cell lymphomas with constitutive NF-kB activation." (PMID 35008340, 2021). "Additionally, lack of MYD88 mutation further supports a diagnosis of MALT lymphoma with plasmacytic differentiation over LPL." (PMID 33499258, 2021). "MyD88 is an adaptor protein involved in Toll-like receptor signaling leading to NF-κB activation in both ABC DLBCL (29%) and in MALT lymphoma (9%)." (PMID 23378931, 2013).
monoclonal gammopathy of undetermined significance (7 papers, 2017 to 2025). "From June 2021 to January 2023, 18 PB MFC studies from patients with an IgM monoclonal gammopathy displaying MYD88 L265P mutation in PB were identified." (PMID 37627180, 2023). "Of the 98 patients with IgM monoclonal gammopathies, the mutational status of MYD88 could be evaluated in 84 patients (84/98 patients, 86%) by tDNA and in 84 patients (84/98 patients, 86%) by cfDNA." (PMID 30026568, 2018). "Being present in 50% of IgM monoclonal gammopathies of undetermined significance (MGUS), MYD88 mutations are most likely a primary event in WM." (PMID 34017329, 2021). "This is the first study to evaluate the feasibility of detecting somatic mutations of MYD88 and CXCR4 in the cfDNA derived from the PB plasma of patients with IgM monoclonal gammopathies." (PMID 30026568, 2018). "The aim of our study was to investigate the role of cfDNA in the characterization of the mutational status of MYD88 and CXCR4 of patients with IgM monoclonal gammopathies." (PMID 30026568, 2018). "In this study, we evaluated the role of peripheral blood (PB) cell-free DNA (cfDNA) in characterizing the mutational status of MYD88 and CXCR4 of patients with IgM monoclonal gammopathies." (PMID 30026568, 2018). "In conclusion, the use of PB cfDNA provides a minimally invasive, but informative and sensitive tool for the assessment of mutational status of MYD88 and CXCR4 of patients with IgM monoclonal gammopathies." (PMID 30026568, 2018). "Both MYD88 and CXCR4 mutations are detected in the bone marrow (BM), although there have been attempts to detect them in CD19+-selected cells in the peripheral blood (PB) of patients with IgM monoclonal gammopathies." (PMID 30026568, 2018).
myelodysplastic syndrome (7 papers, 2013 to 2024). A clonal hematopoietic disorder characterized by dysplasia and ineffective hematopoiesis in one or more of the hematopoietic cell lines. "Lack of MYD88 mutation in LPL/WM, however, predicts worse outcome with higher risk of transformation, therapy-related myelodysplastic syndrome, as well as shorter time to transformation compared to MYD88 mutated patients." (PMID 37951851, 2024). "Recently, aberrant TLR signaling and its downstream effector molecule, Myd88 has been linked to myelodysplastic syndrome (MDS) and acute myeloid leukemia." (PMID 33329562, 2020). "For example, significantly lower antibody responses after vaccination were detected in MyD88-knockout mice, whereas enhanced activation of TLR-MyD88-initiated signaling appears to contribute to the pathogenesis of myelodysplastic syndrome." (PMID 34206078, 2021). "This strategy has demonstrated preclinical efficacy in tumours harbouring MYD88 mutations, and preclinical studies of IRAK1/4 small-molecule inhibitors have reported encouraging preliminary results in melanoma, myelodysplastic syndrome (MDS) and T-cell acute lymphoblastic leukaemia (T-ALL)." (PMID 28829404, 2017).
SARS-CoV infection (7 papers, 2008 to 2023). "TLR signaling pathway provides strong defense against SARS-CoV infection by the myeloid differentiation factor 88 (MyD88)." (PMID 37475019, 2023). "There is evidence that MyD88-independent signaling via the TRIF adaptor protein exerts powerful defense against SARS-CoV infection." (PMID 37475019, 2023). "MyD88 is an essential component of the innate immune response to SARS-CoV infection in mice in vivo." (PMID 31636617, 2019). "The expression analyses of proinflammatory chemokines/cytokines and the lung pathology suggested that MyD88 is critical for early immune/inflammatory responses in lung tissue following SARS-CoV infection." (PMID 19079579, 2008). "Our studies indicate that protection from SARS-CoV infection correlates with MyD88-dependent induction of IL1-β, TNF-α, IL-6, MCP-1, MIP-1α, and RANTES at early times post infection and many of these cytokines/chemokines were upregulated in human SARS-CoV cases." (PMID 19079579, 2008). "Indeed, the MYD88 gene was observed to be highly induced by SARS-CoV infection." (PMID 33363465, 2020). "However, similar to previous reports, we were unable to detect significant induction of type I IFN in lung tissue of either WT or MyD88−/− mice following SARS-CoV infection by qRT-PCR or in serum using a type I IFN bioassay (data not shown) compared to mock-infected control mice." (PMID 19079579, 2008). "Both groups suggested the involvement of TLR7/MyD88/IFNα dependent signaling and further exploration is needed to determine if TLR7 agonist may elicit potent antiviral effects against SARS-CoV infection." (PMID 19505311, 2009). "In the C57BL/6 mouse model of SARS-CoV pathogenesis reported here, we demonstrate MyD88-mediated protection from SARS-CoV infection in the absence of detectable induction of type I interferon." (PMID 19079579, 2008). "Contrary to previous virological studies, we have demonstrated MyD88 plays a crucial role in protection from SARS-CoV infection independent of Type I (α/β) and III (IL-28/29 or interferon lambda) interferon, and the adaptive immune response." (PMID 19079579, 2008). "In addition, MyD88-dependent functions were required for early immune and inflammatory responses in the lung following SARS-CoV infection, and the absence of these early responses correlated with severe SARS-CoV-induced disease and death." (PMID 19079579, 2008).
uveitis (7 papers, 2010 to 2024). An inflammatory process affecting a part of or the entire uvea. "We carried out a two-stage case control study to investigate the association of 13 SNPs of TRIM20, IRF3, IRF7, IRF8, MYD88 and NF-κB1 in two different uveitis entities." (PMID 26794091, 2016).
Anorexia (6 papers, 2011 to 2017). Lack of desire to eat (loss of appetite). "To determine which IL-1β responsive cells are necessary for the resultant fever, lethargy, anorexia, and loss of body weight, we systematically eliminated Myd88-dependent signaling from identified targets." (PMID 29121947, 2017). "Consistent with the phenotypes of TLR2 KO mice, MyD88 deficiency dramatically reduced the Pam3CSK4-induced anorexia and body weight loss." (PMID 27405276, 2016). "Specifically, TLR-4 and MyD88 have been implicated in circadian responses and anorexia respectively." (PMID 21569241, 2011). "Alternatively, it is possible that IL-1β produces anorexia in an IL-1RI mediated, MyD88-independent manner." (PMID 23031643, 2012). "One exception is a recent study reporting that LPS-induced anorexia required hematopoietic MyD88, but not cerebrovascular or neuronal MyD88." (PMID 26790027, 2016). "Although MyD88 expression in neurons has been suggested to play a critical role in the behavioral response to inflammation, we find that IL-1β induced anorexia and lethargy is not contingent upon MyD88-expression in both neurons and astrocytes." (PMID 23031643, 2012).
Cachexia (6 papers, 2021 to 2024). Severe weight loss, wasting of muscle, loss of appetite, and general debility related to a chronic disease. "In two separate reports utilizing different models of cancer cachexia, MyD88 deletion attenuated several measures of cachexia, including anorexia, muscle catabolism, fat loss, hypothalamic inflammation and fatigue." (PMID 34439145, 2021). "Further investigation is needed to characterize the involvement of MyD88, as well as elucidate the specific pathways that modulate skeletal muscle mass in cancer-induced cachexia." (PMID 38334644, 2024). "● MyD88 trigger inflammation that influences cachexia development." (PMID 36465353, 2022). "The role of IL-1β in cachexia is further demonstrated by cachexia studies in which MyD88, which is the universal adaptor protein to all Toll-like receptors (TLRs; except TLR3) and the interleukin 1 receptor family, is implicated in the pathogenesis of cancer cachexia." (PMID 34439145, 2021). "The mRNA was isolated from mouse kidneys and was used to examine the expression levels of signaling proteins, inflammatory cytokines, and genes responsible for inducing cachexia (IL-1β, IL-6, TNF-α, TGF-β, GDF-15, and MYD88)." (PMID 39394174, 2024). "To determine if LCN2 is an inflammation-induced mediator of cachexia, we examined circulating LCN2 levels in both Il-6 and Myd88 knockout mice, as these two inflammatory signaling pathways are critical in the development of several features of cachexia." (PMID 33824339, 2021).